ELOVL7 (ELOVL fatty acid elongase 7)
Diseases named in the same sentence as ELOVL7 in open-access papers (continued):
Sharing a sentence is not in itself a finding about the gene and the disease.
tumor (7 papers, 2021 to 2025). "Hnf4a and Elovl7 showed higher expression level in the tumor bearing mice, compared to control, suggesting that tumor growth in the lung increased the level of genes involved in lipid metabolism in distal hepatocyte tissues in the KL mouse model." (PMID 40236168, 2025). "In the enhancing tumor region (p = 0.004) and tumor core (p = 0.00007), the expression of ELOVL7 was lower than in the peritumoral area." (PMID 36291290, 2022). "The results showed that the expression of ELOVL1 and ELOVL7 in the GBM tumor was lower than in the peritumoral area." (PMID 36291290, 2022). "We showed that ELOVL1 and ELOVL7 expressions were lower in the GBM tumor than in the peritumoral area." (PMID 36291290, 2022). "There was a positive correlation between ELOVL4, ELOVL5, ELOVL6, and ELOVL7 expressions in the GBM tumor." (PMID 36291290, 2022). "Analysis of elongase expression showed that ELOVL1 and ELOVL7 expressions were lower in the GBM tumor than in the peritumoral area." (PMID 36291290, 2022). "The expression of ELOVL7 in the enhancing tumor region was negatively correlated with cigarette packs smoked per year." (PMID 36291290, 2022). "This study examines the expression of elongases ELOVL1, ELOVL2, ELOVL3, ELOVL4, ELOVL5, ELOVL6, and ELOVL7 in GBM tumor samples from 28 patients (16 men and 12 women), using a quantitative real-time polymerase chain reaction (qRT-PCR)." (PMID 36291290, 2022). "ELOVL-7 is induced by androgens and when overexpressed in LNCaP xenograft promotes tumor growth in mice fed high-fat diet (HFD)." (PMID 34386430, 2021). "The 20-carbon n-3 PUFA series has anticancer properties, which may explain the decrease in Elovl7 expression in the glioblastoma tumor as a result of tumor processes." (PMID 37046844, 2023). "Additionally, the expression of ELOVL7 in the peritumoral area was negatively correlated with the expression of this elongase in the enhancing tumor region." (PMID 36291290, 2022). "The same results were obtained when analyzing the enhancing tumor region where ELOVL1 (p = 0.0013) and ELOVL7 (p = 0.004) expressions were lower than in the peritumoral area." (PMID 36291290, 2022). "In the tumor core, the expression of ELOVL1 (p = 0.04) and ELOVL7 (p = 0.013) was lower than in the peritumoral area." (PMID 36291290, 2022). "While previous studies established ELOVL5’s role in promoting ferroptosis through arachidonic acid (AA) synthesis in tumor cells, our work demonstrates for the first time ELOVL7 (rather than ELOVL5) as the dominant elongase in podocyte ferroptosis." (PMID 41285716, 2025). "Additionally, the ELOVL1 expression in the tumor core was positively correlated with ELOVL4, ELOVL5, ELOVL6, and ELOVL7 expressions." (PMID 36291290, 2022). "In vitro FA elongation assay and FA composition analysis showed that ELOVL-7 is preferentially involved in FA elongation of very-long-chain SFAs included in phospholipids and neutral lipids (i.e., cholesterol ester) and when silenced it reduces androgens synthesis and CRPC tumor growth." (PMID 34386430, 2021).
infection (6 papers, 2014 to 2021). The state of being infected such as from the introduction of a foreign agent such as serum, vaccine, antigenic substance or organism. "We find that infection increases ELOVL7 protein levels by a PERK-dependent mechanism with kinetics similar to those of ATF4 expression." (PMID 33947752, 2021). "The expression of ELOVL7 is significantly increased by 24 h post infection, and is >100-fold elevated by 72 h post infection of MRC-5 fibroblasts." (PMID 30699959, 2019). "While ELOVL7 was activated already at 6 h of infection, both ELOVL4 and ELOVL6 displayed a delayed response (activated at 16 h of infection)." (PMID 28993767, 2017). "In this sense, the induction of PTGE2 in the early infection suggests a coordinated function with ELOVL7." (PMID 24812617, 2014). "The elevated expression of ELOVL7 transcript and protein following infection was found to partially depend on the expression of the viral protein UL38, which has previously been demonstrated to manipulate cellular metabolism by indirectly increasing mTOR activity." (PMID 30699959, 2019). "First, we determined whether infection with TB40/E increases ELOVL7 with similar kinetics." (PMID 33947752, 2021). "Further, SREBP activation is required for the HCMV-mediated induction of FA biosynthesis, as well as the enhanced expression of lipogenic genes observed during infection, such as ACC1 and ELOVL7." (PMID 30893762, 2019). "ELOVL7, specifically, was shown to be required for HCMV-induced FA elongation, as its knock-down greatly inhibits the production of VLCFAs during infection." (PMID 30893762, 2019). "Infection with a mutant HCMV virus lacking the UL38 gene fails to induce FA elongation and ELOVL7 expression to the levels observed for wild-type infection." (PMID 30893762, 2019). "Interestingly, the detrimental effects of ELOVL inhibition can be rescued with either VLCFA supplementation or ELOVL7 overexpression, suggesting that HCMV-induced FA elongation is essential for infection and highly dependent on the induction of ELOVLs." (PMID 30893762, 2019). "Next, we confirmed whether TB40/E infection increases ELOVL7 protein levels at 72 and 96 hpi in HFF cells that have not been genetically modified by CRISPR/Cas9 or any other means." (PMID 33947752, 2021).
peripheral neuropathy (1 paper, 2021). A disorder affecting the peripheral nervous system. "Individuals carrying the minor allele (G) at SNP rs186798 in ELOVL7 have a 3.8-fold increased risk to also have a prior diagnosis of peripheral neuropathy." (PMID 33935957, 2021).
ELOVL7 also shares sentences with these, for which no sentence is quoted: breast carcinoma (2 papers); acute myeloid leukemia (1); alcoholic hepatitis (1); alcoholic liver diseases (1); atherosclerosis (1); Cockayne Syndrome A (1); Crohn disease (1); dermatitis (1); hepatocellular carcinoma (1); Latent infections (1); virus infection (1).